FTH1P2 (ferritin heavy chain 1 pseudogene 2)
Synonyms: FTHL2
Gene: Processed pseudogene on chromosome 1 (228,687,415 to 228,687,826, forward strand). Ensembl gene ENSG00000234975.
Diseases named in the same sentence as FTH1P2 in open-access papers:
FTH1P2 is named in the same sentence as 2 diseases in open-access papers, as found by Europe PMC text mining. Sharing a sentence is not in itself a finding about the gene and the disease. The quoted sentences say what the papers report.
prostate carcinoma (1 paper, 2019). A carcinoma that arises from epithelial cells of the prostate gland. "The FTH1 query also resulted in the identification of pseudogenes (FTH1P2, FTH1P8, FTH1P11, FTH1P16) that regulate FTH1 in prostate cancer as well novel miRNAs that may be involved in ceRNA network regulation of FTH1 in prostate cancer." (PMID 31029062, 2019).
FTH1P2 also shares sentences with these, for which no sentence is quoted: lung adenocarcinoma (1 paper).